NOS2P3 (nitric oxide synthase 2 pseudogene 3)
Gene: Transcribed unprocessed pseudogene on chromosome 17 (20,441,027 to 20,446,772, forward strand). Ensembl gene ENSG00000230528.
Diseases named in the same sentence as NOS2P3 in open-access papers:
NOS2P3 is named in the same sentence as 1 disease in open-access papers, as found by Europe PMC text mining. Sharing a sentence is not in itself a finding about the gene and the disease.
NOS2P3 shares sentences with these, for which no sentence is quoted: chronic heart failure (1 paper).